HIF1A (hypoxia inducible factor 1 subunit alpha)
Diseases named in the same sentence as HIF1A in open-access papers (continued):
Sharing a sentence is not in itself a finding about the gene and the disease.
cancer (continued). "In response to hypoxia, cancer cells stabilize HIF-1α, which, in turn, regulates transcription of several target genes, including transcriptional regulators of EMT (SNAIL, ZEB1 and TWIST), glucose transporters, glycolysis enzymes, and VEGF." (PMID 37561190, 2023). "The enhanced uptake driven by HIF-1α stabilization in cancer cells protects them from ROS-induced cell death." (PMID 37256177, 2023). "Upregulation of the transcription factor hypoxia-inducible factor 1-alpha (HIF-1α) in response to low oxygen conditions is also understood to increase glycolytic flux for cancer cells." (PMID 37180129, 2023). "Resultantly, increased HIF1α expression induces proliferation and promotes glycolysis in cancer cells." (PMID 37583933, 2023). "Hypoxia inducible factor-1α (HIF-1α) is a crucial therapeutic target in various diseases, including cancer and fibrosis." (PMID 37615898, 2023). "Cancer cells and CAFs secrete IL-6 to induce HIF-1α expression that modulates downstream genes responsible for chemotherapeutic resistance in cancer cells." (PMID 37627173, 2023). "In an attempt to guarantee the energy supply to cancer cells, HIF-1α activation drives the metabolism for a glycolytic pathway." (PMID 37681875, 2023). "All are involved in cancer progression, HIF-1α regulates the response to acute hypoxia, while HIF-2α and HIF-3α are dominant in the chronic hypoxia response." (PMID 37460927, 2023). "Aurpatene also impeded the hypoxia-inducible factor 1a (HIF-1a), well known nowadays to play a key role in the metabolism of cancer cells, as well as migration, and, more importantly, angiogenesis." (PMID 36829818, 2023). "Accordingly, HIF-1α overexpression has been observed in a variety of human cancers, including colon, and can enhance chemoresistance through the inhibition of apoptosis and senescence and the activation of drug efflux proteins." (PMID 37175841, 2023). "Recent evidence has demonstrated that melatonin exerts its effect on metabolic pathways and cancer treatment by reducing the HIF1α protein." (PMID 37605723, 2023). "Hypoxia influences the expression of a variety of genes (including HIF-1α and von Hippel Lindau protein (pVHL)), resulting in the progression of cancer." (PMID 37180146, 2023). "In this line, allicin and other garlic components have been shown to suppress the HIF-1α pathway in human cancer cells." (PMID 37047205, 2023). "In the meanwhile, the activation of PI3K/AKT/HIF-1α signaling underpins succinate-induced TAM polarization to support cancer cell migration." (PMID 37740232, 2023). "With respect to cancer, aspirin has been shown to decrease levels of HIF-1α in hepatocellular carcinoma leading to a downregulation of GLUT1, decreased glucose import, and reduced cellular proliferation." (PMID 37720350, 2023). "In macrophages and cancer cells, MT1-MMP activates HIF-1α (subunit α of hypoxia-inducible factor 1) by associating with asparaginyl hydroxylase FIH-1 (factor inhibiting HIF1-α) in normoxic conditions through its CT." (PMID 36982142, 2023). "In normoxia, HIF1α is hydroxylated and combined with a cancer suppressor Von Hippel-Lindau (VHL) to undergo ubiquitination process." (PMID 37174078, 2023). "It was shown that upregulation of LY6E expression was associated with poor prognosis in several cancers, and abnormal overexpression of LY6E was found to increase the expression of the HIF-1α gene mainly at the transcriptional level in mouse models." (PMID 37259059, 2023). "Regarding the fact that pVHL suppresses cancer metastasis by inhibiting the stability or activity of HIF1α and other substrates, we next assessed the role of this phosphorylation event in metastasis." (PMID 36813923, 2023). "On the other hand, HIF-1α can activate cellular proliferation by inducing various growth factors in different cancer cells." (PMID 37371055, 2023). "Another protein relevant to the migration and invasion of cancer cells is HIF-1α, which is increased in cancer and hypoxic conditions." (PMID 37760037, 2023).
cancer (continued). "Accumulation of HIF-1α in the cells predominantly correlates with the cells’ metabolic phenotype, as the cancer cells need to reprogram their metabolism, switching between glycolytic and aerobic phenotypes." (PMID 37371055, 2023). "The hypoxia-inducible factor (HIF)-1α pathway contributes greatly to the modulation of hypoxia-related downstream gene expression and pathway activity in cancer cells under hypoxic conditions." (PMID 36925652, 2023). "The hypoxia-induced factor (HIF-1α) expression in cancer cell lines was tested and compared between the conventional hypoxia setup and our automated hypoxia chamber." (PMID 37509306, 2023). "In recent years, vascular normalization therapies have been aimed in part at alleviating hypoxia and inhibition of HIF1α to prevent cancer progression." (PMID 37020036, 2023). "Miar and colleagues reported a minimal role for HIF-1α or HIF-2α in regulating the hypoxic suppression of ISGs in cancer cell lines, but decreased chromatin accessibility of genomic regions relevant for type I IFN pathways." (PMID 37584553, 2023). "Because the role of HIF-1a in cancer is to promote aerobic glycolysis, we tested the effects of XIST on the level of aerobic glycolysis in TC cells by ECAR." (PMID 37036874, 2023). "When these pathways were interpolated with those previously identified in CR and PR/NR, two common pathways were found: HIF-1α signaling and pathways in cancer." (PMID 38138273, 2023). "Data from TCGA database demonstrated that HIF-1a was upregulated in various cancer types, including CCA (CHOL)." (PMID 37821935, 2023). "TAMs also promote the glycolysis and apoptotic resistance in cancer cells through sEVs transferring HISLA to block the degradation of HIF-1α." (PMID 37208722, 2023). "Given the role of HIF1α, it is generally considered an oncogene and has indeed been identified with promote cancer progression in several cancers such as pancreatic cancer, colon cancer and renal cell carcinoma." (PMID 36937454, 2023). "Hypoxic tumor microenvironment leads to inhibition of miR-326 expression in a HIF1α-dependent manner in cancer cells, in turn, promoting ITGA5 expression and hyperactivation of subsequent integrin signaling, resulting in chemotherapy resistance in TNBC cells." (PMID 37583933, 2023). "In some cases, the activity of HIF-1α is toxic in terms of its ability to promote inflammatory diseases or cancer malignancies." (PMID 36831085, 2023). "In detail, activated transcription factors, such as FOXO1, HIF1A, STAT3, and JUN, regulate the expression of TGFB1, TGFB3, IL1B, and TNF, promoting cancer hallmarks associated with these ligands." (PMID 37370765, 2023). "Mitochondrial metabolism can stimulate cancer cell proliferation by altering the activity of transcription factors such as HIF-1α, c-Fos, and c-Jun." (PMID 36901857, 2023). "The expression of hypoxia-inducible factor 1α (HIF-1α) allows adaptation to the hypoxic environment, thus promoting cancer cell survival and progression." (PMID 37108616, 2023). "Under hypoxiaconditions, increased glucose uptake by cancer cells can upregulate the stability of HIF-1α, leading to a weakened antitumor immune response." (PMID 37853445, 2023). "HIF-1α is a pleiotropic transcription factor that promotes the expression of genes for angiogenesis, glycolysis, cancer cell invasion and metastasis, and inflammation." (PMID 37446354, 2023). "In various cancers, including ovarian cancer, FDFT1 is associated with invasion and activates cancer cell metastasis through MMP1, CD44, and AKT/mTOR/HIF1α signaling." (PMID 37107644, 2023). "Despite these canonical effects of HIF-1α activation, there are many examples where cells continue to proliferate despite hypoxic stress, including cancer cells, stem cells, and lung vascular cells." (PMID 37428010, 2023).
cancer (continued). "Thousands of mRNAs are ELAVL1 targets, including factors fostering diverse cancer traits such as proliferation (cyclins A2, B1, D1, and E1), angiogenesis (HIF1a, PTGS2, and VEGFA), survival (BCL2 and MCL1), and invasion (MMP9 and SNAI1)." (PMID 37298909, 2023). "The c-myc and hypoxia-inducible factor 1 (HIF-1α) are abnormally expressed in large quantities in human cancers." (PMID 36851737, 2023). "Changes in the metabolism of cancer cells following overexpression of HIF-1α reduce oxygen consumption to adapt cancer cells to low oxygen conditions." (PMID 37221555, 2023). "HIF-1a enhances hypoxia-related glycolysis in cancer cells by activating the expression of multiple glycolytic enzymes, which is crucial for the growth and proliferation of cancer cells under hypoxic conditions." (PMID 37394582, 2023). "In cohort 2, HIF-1α, TIMP-1, VEGFA, and Ki-67 expression of surgical lung biopsy cases was representatively increased in the cancer cells underlying IP." (PMID 38012636, 2023). "In fact, PKM2 is a transcriptional target of HIF-1α and a key player in the Warburg effect of glycolytic cancer cells." (PMID 37305566, 2023). "Orai3 is induced by hypoxic environments in some cancer cells, for example, the induction of Orai3 under hypoxia is mediated by HIF-1α in the TNBC MDA-MB-468 cell line, increasing the TRPC1 ion channel induced by HIF-1α." (PMID 37833987, 2023). "One study found that POLE2 regulates its downstream oncogene STC1, activates AKT phosphorylation, decreases HIF-1α expression levels, and promotes cancer cell proliferation." (PMID 37240068, 2023). "This warrants a detailed investigation of SREBP1- and HIF1A-targeting miRNAs and their regulation of cancer cell autophagy." (PMID 36835100, 2023). "Activation of HIF‐1α triggers the transcription of genes involved in cancer and immunity, including cytokines IL8, IL6, ANGPTL4, VEGF and PDGF, which are commonly observed in SASP." (PMID 36660875, 2023). "Interplays between AMPK and HIF-1α have been reported that increased AMPK expression and activity are paralleled by the upregulation of HIF-1α in cancer cells." (PMID 38098117, 2023). "A high expression of HIF-1α and/or HIF-2α has been associated with an increased risk of mortality in more than 10 different types of cancer." (PMID 37443821, 2023). "Isoliquiritigenin (25–50 μM) treatment inhibited signaling molecules such as NF‐κB, P13K/Akt, and p38, decreasing MMP‐2, MMP‐9, VEGF, and HIF‐1α expressions leading to reduce the motility of MDA‐MB‐231 cancer cells." (PMID 37132286, 2023). "Further results of the study reported that HIF-1α induces the accretion of LDs in hypoxic cancer cells." (PMID 36761981, 2023). "Cytoplasmic HIF1α expression ranged from 0 to 95% (median 41), while nuclear expression ranged from 0 to 60% (median 0%) of cancer cells." (PMID 36586079, 2023). "Initial evidence suggests that miR-101-mediated downregulation of VHL induces HIF1α-driven cell cycle arrest and apoptosis in cancer cells under normoxia." (PMID 37583933, 2023). "The cancer cell lines were transfected with c-myc or HIF-1α shRNAs for the first 6 h and later infected with ARV at an MOI of 10 for 24 h." (PMID 36851737, 2023). "In tissues, PD-L1 expression by cancer cells was directly related to PD-L1 expression by TILs and macrophages (p < 0.05), and the overexpression of HIF1α and LDH5 (p < 0.05)." (PMID 37067635, 2023). "HIF-1α can also enhance tumor progression by up-regulating the transcription of signal molecules related to antiapoptosis, invasion, and metastasis in cancer cells." (PMID 38139250, 2023). "The expressions of signal transducers and activators of transcription 3 (STAT3), vascular endothelial growth factor (VEGF), and hypoxia-inducible factor-1α (HIF-1α) in cancer cells were examined by immunostaining and analyzed by the Image J analysis system." (PMID 37333486, 2023).
cancer (continued). "Our previous studies showed that inhalational anaesthetics upregulated HIF1α and promoted cell migration and proliferation in several cancer cell lines." (PMID 35953652, 2023). "For example, deletion of HIF-1α in NK cells suppressed the expression of the angiostatic soluble form of VEGF receptor 1 (sVEGFR1) in cancer, increasing VEGF bioavailability in the TME and leading to non-productive angiogenesis." (PMID 36797231, 2023). "Consistent with the known features of Skp2 and HIF-1α as metastasis enhancers in various types of cancers, Mint3 promotes epithelial–mesenchymal transition in a HIF-1α- and Skp2-dependent manner with an enhancing effect on the expression of the Slug protein." (PMID 36831085, 2023). "These hypoxic conditions stimulate the activity and stabilization of the HIF-1a subunit of the transcription factor HIF-1 (hypoxia-inducing factor-1) in both cancer and stromal cells." (PMID 36765912, 2023). "In contrast with several other cancer cells, it has been reported that, in pancreatic ductal adenocarcinoma cells HIF-1α, activation can act as a tumor suppressor." (PMID 36839686, 2023). "Mechanistically, increased hypoxia in cancer tissue masks the miR-542-3p mediated inhibition of HIF1α by upregulating circRBM33 via transcriptional activation by HIF1α itself." (PMID 37583933, 2023). "Hypoxia via HIF-1α can induce the expression of PD-L1 on cancer cells and tumor-infiltrating MDSCs, leading to immune escape." (PMID 37342333, 2023). "Previous studies show that VEGFA is highly expressed in tumors and enhances glycolysis in cancer cells with HIF-1α upregulation." (PMID 37737265, 2023). "Contrary to widespread expression of HIF1α in nearly all cells, HIF2α is selectively expressed in stem cells and endothelial cells of cancer." (PMID 37174078, 2023). "Given that cross talk of canine MGT cells and DH82 is associated with hypoxia, it is considered that HIF-1a contributes to the expression of MRP1 and P-gp to induce drug efflux in canine MGT cells, resulting in anti-cancer drug resistance." (PMID 37369757, 2023). "miR-24 regulates HIF1α expression specifically in breast cancer stem cells (CSCs) and promotes cancer stemness." (PMID 37583933, 2023). "Various studies have reported that hypoxia-activated hypoxia-induced factor-1α (HIF-1α) functions at the gene level to enhance angiogenesis, metastasis, and invasiveness of cancer cells." (PMID 36761981, 2023). "HBO therapy has been shown to regulate the expression of HIF-1α in cancer cells and affect the behavior of CSCs in several ways." (PMID 37886967, 2023). "The combined use of autophagy inhibitors 3-Methyladenine (3-MA) and YC-1 (an inhibitor of HIF-1α), attenuated HMGB1 release in cancer cells, indicating a potential underlying mechanism regulating extracellular levels of HMGB1 and autophagy in OSCC cells." (PMID 37511951, 2023). "Recently, numerous studies have reported the essential roles of HIF-1α in metabolic reprogramming in hypoxic cancer cells." (PMID 38066600, 2023). "HIF-1α-regulated miR-1275 exerts tumorigenic effects on cancer stem cell properties by modulating Notch signaling." (PMID 38022508, 2023). "Since USP29 was reported to regulate the stability of some substrates such as HIF1α and Snail1 in different cancer cells, we also examined the effect of USP29 on these proteins in TNBC." (PMID 36782089, 2023). "HIF-1α stabilization leads to cancer cell acclimatization to hypoxic conditions, increased proliferation, avoidance of apoptosis and therapy resistance in several cancer types." (PMID 36839686, 2023). "Resultantly, increased HIF1α expression induces proliferation through elevated glycolysis in cancer cells." (PMID 37583933, 2023). "Consistent with an important role in cancer cell biology, HIF-1α overexpression strongly correlates with poor prognosis for several solid cancers." (PMID 37305566, 2023).
cancer (continued). "HIF-1α can initiate neovascularisation in hypoxic cancer cells by enhancing the gene expression of VEGF by or by utilizing lactate as a signalling molecule." (PMID 36761981, 2023). "Hypoxia-inducible factor-1 alpha (HIF-1α) is a transcription factor that plays a key role in the response of cancer cells to hypoxia." (PMID 37886967, 2023). "Taken together, these findings demonstrate that tanshinone-mediated HIF-1α emerges as an alternative cancer treatment." (PMID 37964867, 2023). "Previous studies have proven that HIF-1a is positively related to the expression of lipogenic enzymes and promotes fatty acid synthesis in carcinoma." (PMID 37821935, 2023). "Our in vitro analysis clearly showed that NBO2 water suppressed hypoxia-induced radiation resistance in cancer cell lines via the downregulation of HIF-1α accumulation under hypoxic conditions." (PMID 35743281, 2022). "Transcription factor hypoxia-inducible factor-1α (HIF-1α) has an essential effect on cancer cellular metabolism." (PMID 35280516, 2022). "In cancer cells the main feature in response to hypoxia is induction of HIF-1α as well as its downstream target to enhance blood vessel formation, and aggression." (PMID 35449150, 2022). "Clinical studies have revealed that HIF-1α plays a crucial role in cancer progression, metastasis, and poor prognosis." (PMID 35592530, 2022). "Our results confirmed that HSP90 and HIF-1α protein expression under normoxia was higher in CoCl2-treated cancer cells than in untreated cells." (PMID 35408505, 2022). "The role of P4HA1 in PDAC was revealed, which can regulate HIF1α activity and led to high proliferation, chemoresistance, and cancer cell stemness." (PMID 36291742, 2022). "METTL3 was demonstrated to induce aerobic glycolysis by regulating the expression of adenomatous polyposis coli (APC) or HIF-1α in various cancers." (PMID 35757505, 2022). "Previous studies in cancer cells have identified hypoxia-associated factor (HAF), that selectively binds and degrades HIF-1α in an oxygen-dependent manner, whereas its binding to HIF-2α selectively increases this factor transactivation." (PMID 36482296, 2022). "HIF-1α overexpression is correlated with disease progression, chemo-radio-resistance, and increased patient mortality in certain cancers." (PMID 35198082, 2022). "Consistently, suppressing HIF-1α expression by Rhein and Emodin compounds mitigates cancer cell proliferation and CC in a dose- and time-dependent mode." (PMID 35205167, 2022). "HIF-1α as an upstream molecule of viperin was expressed at basal levels in cancer cell lines under normoxia." (PMID 36227691, 2022). "Together with the evidence presented here, this suggests that there is a certain correlation between HIF1α expression and the infiltration of various immune cells in the pan-cancer microenvironment." (PMID 35860430, 2022). "These exosomes transfers Wnt4 depending on HIF-1α which in turn activates the β-catenin signaling pathway and facilitates metastasis, contributing to cancer progression." (PMID 35496046, 2022). "Mounting data suggest that HIF-1α is one of the main culprits in the regulation of various hallmarks of cancer." (PMID 36014432, 2022). "In pancreatic cancer, the hypoxic induction of a HIF-1α-stabilizing circular RNA (cirZNF91) in cancer-secreted exosomes was reported to promote chemoresistance in normoxic cancer cells." (PMID 36176760, 2022). "We demonstrate that hypoxic signaling is activated in early PINs, a phenomenon previously reported in malignant tumors, and identify HIF1A as a major driver of PIN progression." (PMID 35867798, 2022). "On the other hand, through these metabolic alterations, HIF-1α promotes insulin resistance and obesity in most of the cancer patients." (PMID 36014432, 2022). "The HIF-1α contributes to the Warburg observed in cancer cells, facilitating the switch from oxidative phosphorylation to glycolysis." (PMID 36182907, 2022).